SPRED3 (sprouty related EVH1 domain containing 3)
Description:
Tyrosine kinase substrate that inhibits growth-factor-mediated activation of MAP kinase (By similarity). Inhibits fibroblast growth factor (FGF)-induced retinal lens fiber differentiation, probably by inhibiting FGF-mediated phosphorylation of ERK1/2 (By similarity). Inhibits TGFB-induced epithelial-to-mesenchymal transition in lens epithelial cells (By similarity).
Synonyms: Spred-3; EVE-3
Tractability: Antibody: UniProt places it where antibodies can reach, with medium confidence; its Gene Ontology location is reachable by antibodies, with medium confidence; the Human Protein Atlas places it where antibodies can reach. PROTAC: UniProt records ubiquitination sites on it.
Gene: Protein-coding gene on chromosome 19 (38,388,421 to 38,399,588, forward strand). Ensembl gene ENSG00000188766.
Subcellular location: Cell membrane
Subcellular location (Human Protein Atlas): Nucleoplasm; Plasma membrane
Pathways (Reactome):
Disease: RAS signaling downstream of NF1 loss-of-function variants
Signal Transduction: Regulation of RAS by GAPs
Gene Ontology:
Molecular function: protein kinase binding
Biological process: negative regulation of epithelial to mesenchymal transition; negative regulation of ERK1 and ERK2 cascade; negative regulation of lens fiber cell differentiation; negative regulation of transforming growth factor beta receptor signaling pathway; negative regulation of intracellular signal transduction; regulation of signal transduction
Cellular component: plasma membrane; membrane
Genetic constraint (gnomAD): Loss-of-function variants: 23 observed, 21.16 expected, observed/expected ratio (o/e) 1.09, 90% interval 0.78 to 1.54. The synonymous counts are far from expectation, so gnomAD's model fits this gene poorly and the ratio says little. Missense variants: 584 observed, 413.38 expected, observed/expected ratio (o/e) 1.41, 90% interval 1.32 to 1.51. Synonymous variants: 302 observed, 189.64 expected, observed/expected ratio (o/e) 1.59, 90% interval 1.45 to 1.75.
Homologues: Orthologues: chimpanzee SPRED3 (99% identical), macaque SPRED3 (99% identical), rabbit SPRED3 (97% identical), dog SPRED3 (97% identical), guinea pig SPRED3 (95% identical), mouse Spred3 (95% identical), rat Spred3 (94% identical), pig SPRED3 (85% identical), zebrafish spred3 (48% identical), tropical clawed frog spred3 (47% identical), Drosophila melanogaster Spred (31% identical), Caenorhabditis elegans unc-34 (21% identical), and 1 more. Paralogues in human: SPRED2 (40% identical), SPRED1 (37% identical), VASP (19% identical), ENAH (19% identical), EVL (18% identical).
Diseases named in the same sentence as SPRED3 in open-access papers:
SPRED3 is named in the same sentence as 26 diseases in open-access papers, as found by Europe PMC text mining. Sharing a sentence is not in itself a finding about the gene and the disease. The quoted sentences say what the papers report.
thyroid cancer (4 papers, 2019 to 2025). "Mechanistically, SPRED3 has been implicated in promoting thyroid cancer cell proliferation via the nuclear factor-κB (NF-κB) signaling pathway." (PMID 40806788, 2025). "The objective of this study was to establish the diagnostic value of SPRED3 expression in patients with thyroid cancer (THCA) and its molecular function, as well as its association with immune infiltration." (PMID 38402263, 2024). "In this study, we validated the diagnostic value of SPRED3 in a specific subgroup of patients with thyroid carcinoma (THCA) through Kaplan‒Meier curve analysis." (PMID 38402263, 2024). "Functional enrichment analysis was subsequently performed to elucidate the molecular mechanisms underlying the regulatory effects of the SPRED3 gene on thyroid carcinoma." (PMID 38402263, 2024). "Further studies are hence necessary to thoroughly grasp the molecular mechanisms of SPRED3 in the thyroid gland within the context of MAPK signaling—a key signaling pathway in thyroid cancer." (PMID 40806788, 2025). "SPRED3 (Sprouty-related EVH1 domain containing 3) mutants are depicted in various cancers, however, nothing is known about its biofunction in thyroid cancer (THCA)." (PMID 39227612, 2024). "Compared with those in noncancerous thyroid tissue, the gene and protein expression levels of SPRED3 were found to be elevated in thyroid carcinoma tissues." (PMID 38402263, 2024). "The results showed that SPRED3 expression was significantly upregulated in thyroid carcinoma tissues." (PMID 38402263, 2024). "The bioinformatics data were subsequently validated through immunohistochemistry to confirm the expression of SPRED3 in thyroid carcinoma and corresponding paracancerous tissues." (PMID 38402263, 2024). "The results revealed high expression of SPRED3 in 34 out of 67 patients with thyroid carcinoma and in 13 of 67 paired para-cancerous normal tissues (P < 0.001)." (PMID 38402263, 2024). "The difference in the expression of the SPRED3 gene between thyroid carcinoma (THCA) tissues and normal tissues was analyzed using data from The Cancer Genome Atlas (TCGA) and further validated through immunohistochemistry." (PMID 38402263, 2024). "Moreover, more recent findings link SPRED3 to thyroid carcinoma, where its overexpression correlates with poor clinical outcomes and advanced tumor stages." (PMID 40806788, 2025). "Although recent in vitro studies have suggested that SPRED3 could serve as a potential biomarker in thyroid carcinoma, the physiological role and molecular mechanism of SPRED3 in this context have yet to be fully elucidated." (PMID 40806788, 2025). "Moreover, the correlations between SPRED3 and clinical indicators in patients with thyroid carcinoma were further substantiated through the collection of clinicopathological data." (PMID 38402263, 2024). "Furthermore, we examined the correlation between SPRED3 expression and clinical prognosis in different subgroups of thyroid carcinoma patients." (PMID 38402263, 2024). "Furthermore, the expression of SPRED3 in thyroid carcinoma exhibited significant correlations with tumor location, histological grade, pathological stage, and tumor node metastasis classification (TNM) stage." (PMID 38402263, 2024). "Furthermore, to assess the potential of SPRED3 as a prognostic marker for patients with thyroid carcinoma (THCA), RNAseq and clinical data from the TCGA-THCA datasets were obtained and organized using the STAR process." (PMID 38402263, 2024). "Furthermore, bioinformatic analyses suggest that SPRED3 may serve as a prognostic biomarker in thyroid carcinoma, possibly influencing extracellular matrix organization and immune cell infiltration." (PMID 40806788, 2025).
cervical carcinoma (3 papers, 2019 to 2024). A carcinoma arising from either the exocervical squamous epithelium or the endocervical glandular epithelium. "SPRED3, is reported to have an influence on EGFR mutated NSCLC, glioblastoma, and cervical carcinoma." (PMID 38217548, 2024). "We detected previously unreported recurrent mutations in cervical cancer in GPX1, MSN, FAS, KRT8, and SPRED3, all genes known to modulate tumorigenic processes." (PMID 34620846, 2021). "The increased sample size enabled identification of SMGs previously unreported in cervical carcinoma including NBPF10 (8%), RANBP2 (6%), MSN (6%), KRT8 (6%), POTEC (6%), ZC3H11A (4%), BMS1 (4%), GPX1 (3%), OTOP1 (3%), DNAH12 (2%), COIL (2%), TBC1D26 (2%), SPRED3 (2%), FAM115A (2%), and ARIH1 (1%)." (PMID 34620846, 2021).
head and neck squamous cell carcinoma (1 paper, 2022). A squamous cell carcinoma that arises from any of the following anatomic sites: lip and oral cavity, nasal cavity, paranasal sinuses, pharynx, larynx, and salivary glands. "In patients with head and neck squamous cell carcinoma (HNSCC), upregulation of CALM1, CYCS, THBS1, MYC, GATA6, and SPRED3 was strongly associated with a poor prognosis." (PMID 36239104, 2022).
non-small cell lung carcinoma (1 paper, 2024). A group of at least three distinct histological types of lung cancer, including non-small cell squamous cell carcinoma, adenocarcinoma, and large cell carcinoma. "Recent research has revealed that a loss-of-function mutation in SPRED3 is responsible for activating the Ras/Raf/MAPK pathway in non-small cell lung cancer (NSCLC) cells." (PMID 38402263, 2024).
papillary thyroid cancer (1 paper, 2024). "High SPRED3 expression was associated with unfavorable clinical outcomes, advanced tumor characteristics, and traditional molecular markers of papillary thyroid cancer in THCA patients." (PMID 39227612, 2024). "In addition, we estimated the SPRED3 expression difference in the traditional molecular markers of papillary thyroid cancer such as BRAFV600E-RAS score (BRS), Thyroid differentiation score (TDS) and ERK activation level (i.e., ERK score)." (PMID 39227612, 2024).
Primary hypothyroidism (1 paper, 2025). A type of hypothyroidism that results from a defect in the thyroid gland. "Using this KO model, we demonstrated that SPRED3-deficient mice not only exhibit reduced body weight but also develop primary hypothyroidism, as evidenced by significantly elevated TSH levels and decreased T4 serum concentrations." (PMID 40806788, 2025). "To determine whether the observed thyroidal hormonal imbalance and the associated primary hypothyroidism are linked to MAPK pathway modulation dependent on functional SPRED3, we performed Western blot analysis with thyroid lysates from SPRED3 WT and KO mice." (PMID 40806788, 2025). "We also observed that SPRED3 KO mice exhibited significantly elevated TSH levels and reduced T4 concentrations, collectively indicating primary hypothyroidism." (PMID 40806788, 2025).
prostate carcinoma (1 paper, 2023). A carcinoma that arises from epithelial cells of the prostate gland. "SPRED3 is suggested to be a negative regulator of RAS/MAPK signaling but has not been studied in prostate cancer." (PMID 36809527, 2023).
renal chromophobe cell carcinoma (1 paper, 2024). "Conversely, SPRED3 was found to be expressed at low levels in renal chromophobe cell carcinoma (KICH) cells." (PMID 38402263, 2024).
sarcoma (1 paper, 2025). A usually aggressive malignant neoplasm of the soft tissue or bone.
thyroid (1 paper, 2024). "The results showed that SPRED3 expression significantly differed according to clinical stage (T1/2 vs. T3/4), lymph node invasion (N0 vs. N1), primary tumor tissue type, external thyroid gland invasion, tumor residue, tumor location and previous thyroid history." (PMID 38402263, 2024).
thyroid tumor (1 paper, 2024). A benign or malignant neoplasm affecting the thyroid gland. "Additionally, there were significant correlations between the expression level of the SPRED3 gene and the infiltration of various immune cells (eosinophils, central memory T cells, neutrophils, macrophages, and NK cells) within the thyroid tumor microenvironment." (PMID 38402263, 2024).
tumor (4 papers, 2023 to 2024). "The results suggest that overexpression of SPRED3 is associated with dyscohesive cells at the periphery of the tumor and at its invasive front, which contribute to tumor progression by activating the MAPK signaling pathway." (PMID 39227612, 2024). "Among AR-association gained genes, new candidate genes that strongly associated with aggressive tumor traits were sprouty related EVH1 domain containing 3 (SPRED3), transmembrane serine protease 11F (TMPRSS11F) and solute carrier family 1 member 1 (SLC1A1)." (PMID 36809527, 2023). "Therefore, SPRED3 might cause NF-κB activation to increase tumor cell malignant phenotypes and thereby lead to tumorigenesis in THCA." (PMID 39227612, 2024). "The results showed that SPRED3 depletion retarded tumor growth and reduced the tumor weight compared with the WT group." (PMID 39227612, 2024). "The experimental findings demonstrated a positive correlation between the expression level of SPRED3 and the relative abundance of 24 immune cell types within the tumor microenvironment." (PMID 38402263, 2024). "We conducted a comparative examination of SPRED3 expression in tumor tissue and corresponding paracancerous normal thyroid tissue from THCA patients (n = 58)." (PMID 38402263, 2024). "Particularly, THCA tissues exhibited robust SPRED3 expression compared to corresponding normal tissues and tumor-free tissues from the TCGA database." (PMID 39227612, 2024). "Comparison of SPRED3 expression in the high and low groups showed that SPRED3 expression was higher in the high BRS or ERK tumor groups, while lower in the high TDS tumor groups." (PMID 39227612, 2024). "In vivo experiments in mice confirmed the inhibitory effect of SPRED3 depletion on tumor growth." (PMID 39227612, 2024). "Paraffin-embedded tumor tissues were collected for the detection of SPRED3 expression." (PMID 38402263, 2024). "More importantly, SPRED3 overexpression promoted THCA cell proliferation, while SPRED3 curbed the tumor cell proliferation and tumor growth in vivo." (PMID 39227612, 2024). "Therefore, SPRED3 might be a tumor suppressor during cancer malignancy." (PMID 39227612, 2024). "In short, we found that SPRED3 was overexpressed in THCA and confirmed its tumor-promoting role in partly activating the NF-κB signaling pathway." (PMID 39227612, 2024). "(A) SPRED3 expression between high and low BRS, TDS and ERK tumor groups." (PMID 39227612, 2024). "Notably, high SPRED3 expression correlated with pathological prognostic indicators of THCA, including advanced tumor depth (T stage) and nodal involvement (N-Stage)." (PMID 39227612, 2024).
cancer (2 papers, 2022 to 2024). A tumor composed of atypical neoplastic, often pleomorphic cells that invade other tissues. "The expression of SPRED3 was assessed in TCGA pan-cancer tissues and normal paratumor tissues." (PMID 39227612, 2024). "The results indicated an overall increase in SPRED3 expression across most cancer types." (PMID 39227612, 2024).
SPRED3 also shares sentences with these, for which no sentence is quoted: lung cancer (2 papers); colorectal cancer (1); endometrial cancer (1); glioblastoma (1); glioma (1); hypothyroidism (1); liver cancer (1); metabolic disorders (1); Obesity (1); ovarian carcinoma (1); pancreatic cancer (1); renal carcinoma (1); stomach cancer (1).